SIRT1 (sirtuin 1)
Diseases named in the same sentence as SIRT1 in open-access papers (continued):
Sharing a sentence is not in itself a finding about the gene and the disease.
atherosclerosis (continued). "Sirt1 maintains endothelial function by reducing oxidative stress and inflammation, thereby suppressing atherosclerosis 86, while also regulating VSMC dynamics to improve vasodilation." (PMID 40225574, 2025). "We set out to compare the levels of sC5b-9, RGC-32, and SIRT1 in the three groups of patients in order to identify biomarkers of unstable plaque and their role in atherosclerosis." (PMID 40507709, 2025). "Studies have shown that resveratrol down-regulates the expression of NF-κB p65 and p38 MAPK, while up-regulating the expression of SIRT1, thereby reducing vascular inflammatory damage and atherosclerosis." (PMID 39125368, 2024). "SIRT1 is known to exert a protective role against inflammation and oxidative stress, which are important elements in atherosclerosis development." (PMID 39680523, 2024). "In sum, our study directly proved Larp7 overexpression activates Sirt1 and suppresses cellular senescence pathway, thereby exhibiting a therapeutic role in atherosclerosis." (PMID 38818612, 2024). "Through SIRT1-mediated deacetylation of the PGC-1α pathway, SRT1720 mitigates OA-induced atherosclerosis associated with VSMC senescence and mitochondrial dysfunction." (PMID 38999988, 2024). "Sirt1 safeguards against atherosclerosis by inhibiting endothelial cell dysfunction, senescence of vascular smooth muscle cells (VSMCs) and the formation of macrophage foam cells." (PMID 38818612, 2024). "There is an urgent need to identify small-molecule drugs that selectively target SIRT1 for the treatment of atherosclerosis." (PMID 38202844, 2024). "In this study, paeonol, a potential anti-inflammatory agent for the treatment of atherosclerosis, potently enhanced the expression of the SIRT1 protein in vivo and in vitro." (PMID 38202844, 2024). "Here, SIRT1 was identified as a potential target of paeonol having anti-senescence and anti-atherosclerosis activity." (PMID 38202844, 2024). "The predicted dysregulation of downstream targets following the inhibition of SIRT1 and ETS1 was also associated with increased inflammation and atherosclerosis, as validated by animal models studies." (PMID 39125657, 2024). "In fact, exercise training prevents the development of atherosclerosis through SIRT1 activation and oxidative stress inhibition under HHcy situation." (PMID 39360276, 2024). "Animal models have similarly implicated SIRT1 in the regulation of EC proliferation and senescence, thus signifying a protective role of SIRT1 in atherosclerosis." (PMID 39125657, 2024). "SIRT1 role in regulating eNOS and oxidative stress is crucial for understanding its role in thrombosis and atherosclerosis pathways." (PMID 38304233, 2023). "A previous study demonstrated that quercetin, abundant in AME, modulated AMPK/SIRT1 signaling in a rodent model of atherosclerosis." (PMID 37299522, 2023). "SIRT1 has been reported to play an endothelial-protective role, maintaining endothelial function, preventing endothelial senescence, and ameliorating atherosclerosis." (PMID 37894840, 2023). "In atherosclerosis, the promotion of autophagy and apoptosis of peritoneal macrophages through the activation of SIRT1 via the NAD+-mediated EB transcription factor promotion pathway was documented." (PMID 37630770, 2023). "Overall, these findings suggest that SIRT1 plays a crucial role in regulating lipid metabolism and inflammation in the context of atherosclerosis, making it a potential therapeutic target for the prevention and treatment of this disease." (PMID 38304233, 2023).
atherosclerosis (continued). "Long-term administration of curcumin in a mouse model of atherosclerosis induced by a high-fat diet protected against decreased SIRT1 expression, senescent cell accumulation, and vascular inflammation." (PMID 37630770, 2023). "We suggest that the observed increase in SIRT1 operates as a mediator and thus contributes to protection against vascular ageing and atherosclerosis." (PMID 36979007, 2023). "SIRT1 reduces the expression of lectin-like oxLDL receptor-1 by inhibiting NF-κB signaling pathway, thus reducing oxLDL uptake and alleviating atherosclerosis." (PMID 36632457, 2023). "Physiologically SIRT1 is positioned at a chrono-metabolic juncture and is reported to be functional at several stages of initiation and development of atherosclerosis." (PMID 37561715, 2023). "To identify an effective target for anti-atherosclerosis therapy through SIRT1, we analyzed the possible direct targets of miR-200a-3p and SIRT1 using bioinformatics." (PMID 37874693, 2023). "Down-regulation of sirtuin-1 contributes to ovariectomy -induced arterial senescence and atherosclerosis in female apolipoprotein (Apo)E−/− mice, whereas oestrogen or a selective oestrogen receptor modulator up-regulate sirtuin-1 and counter these changes." (PMID 37153459, 2023). "Mice with endothelium-specific overexpression of SIRT1 are protected against diet-induced atherosclerosis in hyperlipidemic Apoe−/− mice, with improved aortic NO production independent of blood lipid and glucose levels." (PMID 37894840, 2023). "In summary, our data demonstrate that miR-9 contributes to the inhibition effect of DMY on M1 macrophage polarization, at least in part, by targeting SIRT1 and activating the NF-κB pathway in atherosclerosis." (PMID 37234960, 2023). "Since most of the natural compounds described here exhibit pleiotropic effects, establishing a direct link between SIRT1 activation and the prevention or reduction of atherosclerosis is quite challenging." (PMID 38038821, 2023). "Considering the complex clinical trial experience of SIRT1 activators, further research is needed to explore the potential therapeutic implications of these findings in the context of atherosclerosis and vascular aging." (PMID 37894840, 2023). "SIRT1 activation has been demonstrated to mitigate or prevent atherosclerosis through various mechanisms." (PMID 38038821, 2023). "Here, we provided evidence that DMY relieved vascular inflammation and repressed M1 macrophage polarization in atherosclerosis through modulating the miR-9/SIRT1/NF-κB signal pathway." (PMID 37234960, 2023). "In the present review, we discuss novel insights into the effects of natural molecules considered as SIRT1-activating compounds and their impact on atherosclerosis in the last 5 years." (PMID 38038821, 2023). "MiR-217 has also been associated with macrophage apoptosis in endothelium-specific knock-in mouse models for atherosclerosis, where it was reported to downregulate SIRT1 in vivo." (PMID 38136977, 2023). "Indicatively, miR-217 has been correlated with deregulated macrophage apoptosis in an endothelium model for atherosclerosis in mice, where it was found to downregulate SIRT1 in vivo." (PMID 38136977, 2023). "The purpose of this review is to summarize the most recent findings investigating the impact of several natural sirtuin (SIRT) activators, particularly SIRT1, on atherosclerosis." (PMID 38038821, 2023). "Quercetin modulates AMPK/SIRT1/NF-κB pathway to inhibit inflammatory responses in diabetic high fat diet-induced atherosclerosis in the carotid artery of rats." (PMID 35935939, 2022).
atherosclerosis (continued). "Selective SIRT1 activators have potential clinical applications in atherosclerosis, acute renal injury, and Alzheimer’s disease." (PMID 35566069, 2022). "SIRT1 exerts many functions in VSMCs, including protecting against DNA damage, inhibiting atherosclerosis, inducing cell differentiation, and protecting against cell senescence and vascular aging." (PMID 36479179, 2022). "A functional mechanism supported by the collaboration between AMPK and sirtuin-1 has been described as counteracting atherosclerosis in vivo mice models." (PMID 36359402, 2022). "Some natural products such as Araloside C., Salidroside, and Berberine have potential anti-atherosclerosis effects by targeting SIRT1 and increasing its expression to regulate autophagy." (PMID 36188570, 2022). "Compared to SIRT1, a relatively limited number of studies have explored the roles of other SIRTs in atherosclerosis." (PMID 36581622, 2022). "Combined with the report that SIRT1/FoxO1 pathway enhances autophagy flux in order to prevent atherosclerosis and arterial thrombosis, we believe SIRT1 plays a critical role in DMC." (PMID 35508613, 2022). "In recent years, senescence and the related enzyme SIRT1 have been considered new directions for studying autophagy and atherosclerosis." (PMID 36188570, 2022). "SIRT1 also exerts a beneficial effect against the development of atherosclerosis and other diabetic complications." (PMID 35956321, 2022). "SIRT1 is a well-known anti-aging factor in vascular diseases, and our previous studies demonstrated the role of SIRT1 in preventing atherosclerosis, hypertension, and abdominal aortic aneurysm." (PMID 35855341, 2022). "Among the different processes in which miR-199a-5p participate, several targets are implicated in atherosclerosis including ABCA1, ABCG1, Cav-1, HIF1A, CD38, NCOR1, and SIRT1 in human and mouse." (PMID 36407436, 2022). "Quercetin inhibited oxidative stress responses of high fat diet-induced atherosclerosis of rat by AMPK/SIRT1/NF–κB signaling." (PMID 36145273, 2022). "On the contrary, inhibition of SIRT1 leads to impaired autophagy, which in turn aggravates atherosclerosis." (PMID 36188570, 2022). "The results showed that SIRT1 was weakly expressed in the atherosclerosis model in vitro, and liquiritin increased SIRT1 expression in ox-LDL-induced hVSMCs." (PMID 35038972, 2022). "In conclusion, the protective properties of sirtuin 1 against oxidative stress reduce endothelial dysfunction, inflammation, remodeling of arterial walls, vascular aging, atherosclerosis, and heart damage." (PMID 34439776, 2021). "miR-34a can develop atherosclerosis via inhibiting cell cycle and SirT1 protein expression, inducing endothelial cell senescence and repressing cell proliferation." (PMID 34552965, 2021). "It should be noted that the protective effect of these dietary supplements on atherosclerosis development is also connected to the inhibition of inflammation, including as a result of SIRT1 activation." (PMID 34940525, 2021). "The circ-Sirt1 level was significantly decreased in the vascular tissue of patients with atherosclerosis or hypertension." (PMID 34977164, 2021). "Based on these findings, synthetic SIRT1 activators or resveratrol, which is one of the potent natural compounds activating SIRT1, are reasonable candidates for mitigating deleterious effects of TET2 mutations on hematopoiesis, atherosclerosis, and CVD." (PMID 33114351, 2020). "A study revealed that atherosclerosis in SIRT1+/‐Apo E−/− mice is decreased significantly compared with ApoE−/− counterparts." (PMID 32627301, 2020). "Taken together, the regulatory effect of SIRT1 on VSMC proliferation and migration relies on the cell cycle arrest at G1/S transition and the repression of MMPs, which potentiates SIRT1 as an intervention target for early atherosclerosis prevention." (PMID 33117155, 2020).
atherosclerosis (continued). "In the past decades, the role of SIRT1, a longevity-related molecule, in atherosclerosis development has been widely studied not only in VSMCs but also in ECs and macrophages, since aging is the independent risk factor for CAD." (PMID 33117155, 2020). "In the context of atherosclerosis, SIRT1 was shown to have a protective effect on human and rodent vascular cells against DNA damage." (PMID 33274583, 2020). "The in vivo, in vitro and molecular docking results, suggest that AsC prevented foam cell and atherosclerosis formation by targeting and upregulating Sirt1 expression." (PMID 31986489, 2020). "In STZ-diabetic mice, acacetin significantly upregulated the decreased signaling molecules (i.e. SOD, Bcl-2, PGC-1α, pAMPK, Sirt3 and Sirt1) in aorta tissue and attenuated atherosclerosis." (PMID 33519472, 2020). "On the contrary, SIRT1 has been demonstrated to have a protective role in vascular pathologies as it can inhibit neointima formation, atherosclerosis, and vascular SMC hypertrophy (38, 66, –, 68)." (PMID 31932306, 2020). "Rapamycin attenuated atherosclerosis induced by dietary cholesterol in ApoE−/− mice via upregulating SIRT1 and inactivating YAP." (PMID 32081881, 2020). "Statins have demonstrated antioxidative effects on atherosclerosis through the inhibition of Sirt1 expression." (PMID 32762716, 2020). "Altogether, AsC attenuates foam cell formation and lessens atherosclerosis by modulating macrophage polarization via Sirt1-mediated autophagy." (PMID 31986489, 2020). "Sirt1 plays important roles in the progression of the age-related diseases atherosclerosis and osteoporosis." (PMID 32762716, 2020). "Sirt1, a nicotinamide adenine dinucleotide-dependent protein deacetylase, has gained attention for its protective effects against atherosclerosis." (PMID 31986489, 2020). "Previous studies revealed that UF induces SIRT1 to favor autophagy, modulate homeostasis, and antagonize atherosclerosis." (PMID 32081881, 2020). "In conclusion, the results of this study, along with findings from previous reports, confirmed the protective role of Sirt1 in atherosclerosis." (PMID 33250679, 2020). "It has been reported that SIRT1 plays a pivotal role in the regulation of cellular proliferation and invasion in atherosclerosis and angiogenesis." (PMID 32337837, 2020). "SIRT1 can inhibit vascular remodeling, stiffness, and functions in protection against atherosclerosis and vascular calcification in mice and is indicative that SIRT1 has protective roles in vascular injury diseases." (PMID 33101015, 2020). "SIRT1 has been reported to exert important protective effects against aging, atherosclerosis, hypertrophic stresses and ischemia/reperfusion injury." (PMID 31076562, 2019). "Researchers have identified a possible new tool, the signaling molecule SIRT1, to fight vascular diseases such as atherosclerosis, hardening of the arteries." (PMID 31023999, 2019). "There exist several studiesevaluating sirtuin 1 levels in human atherosclerosis using different methodologicalmanners." (PMID 31291416, 2019). "SIRT1 exerts protective roles in atherosclerosis through suppression of endothelial oxidative stress and foam cell formation." (PMID 31146723, 2019). "Resveratrol was reported to protect HUVECs from atherosclerosis by upregulating Sirt1 levels, restoring lysosomal function, enhancing autophagic flux, and accelerating Ox-LDL degradation through the autophagy-lysosome degradation pathway." (PMID 28546854, 2017). "SIRT1 activates endothelial nitric oxide synthase and protects vascular smooth muscle cells against DNA damage, medial degeneration, and atherosclerosis." (PMID 28659816, 2017).
atherosclerosis (continued). "Reduced SIRT1 expression is associated with increased apoptosis; VSMC apoptosis can increase atherosclerosis, with an increased necrotic core, reduced fibrous cap thickness, and foci of inflammation within the cap." (PMID 29299128, 2017). "This interplay results in a vicious cycle of Sirt1 inactivation and oxidative stress/inflammation in vascular tissue, resulting in vascular aging and atherosclerosis." (PMID 27744418, 2016). "In this review, we discuss the protective role of Sirt1 in the pathophysiology of vascular aging and atherosclerosis." (PMID 27744418, 2016). "SIRT1 downregulates expression of the NFκB signaling pathway during atherosclerosis by deacetylating RelA/p65-NFκB in macrophages and decreasing foam cell formation." (PMID 26904696, 2016). "SIRT1 exerts protective effects against endothelial cells dysfunction, inflammation and atherosclerosis, indicating an important role on myocardial infarction (MI) pathogenesis." (PMID 25706717, 2015). "Sirt1 was reported to prevent atherosclerosis by potentially regulating the degree of autophagy to match current cellular needs with real-time metabolic status." (PMID 24378473, 2014). "Sirtuin1 (Sirt1), a member of the conserved sirtuin family and a key regulator in the progression of atherosclerosis exerts protective effects by regulating autophagy, a well-known survival mechanism." (PMID 24378473, 2014). "Different effect of genetic polymorphisms in the SIRT1 on carotid atherosclerosis in female and male populations might be partial explained by the different role of sex hormones in regulation of gene expression or important role of sex-specific risk factors for atherosclerosis." (PMID 25273948, 2014). "Worthy of note is that the endothelium-specific overexpression of SIRT1 decreased atherosclerosis in apoE−/− mice." (PMID 25143940, 2014). "Taken together, these data suggest that the repression of PAI-1 plays a crucial role in the anti-aging effect of SIRT1, leading to protection against vascular function decline and age-related cardiovascular diseases, such as atherosclerosis." (PMID 25040736, 2014). "SIRT1 is a major molecule for the regulation of inflammation and mitigation of oxidative stress in chronic diseases such as atherosclerosis and chronic obstructive pulmonary disease." (PMID 24624081, 2014). "It will be interesting to further elucidate the involvement of these proteins in the regulation of replicative endothelial senescence and atherosclerosis by SIRT1." (PMID 25040736, 2014). "In the present study, we demonstrated for the first time to our knowledge that SIRT1 inhibition of PAI-1 expression protects against replicative senescence of endothelial cells, associated with vascular aging and the development of atherosclerosis." (PMID 25040736, 2014). "This study was therefore designed to investigate the role of Sirt1 in the development of atherosclerosis." (PMID 23382833, 2013). "Sirt1 decreases macrophage foam formation by inhibiting cholesterol uptake, suggesting that Sirt1 plays a protective role in atherosclerosis." (PMID 24069345, 2013). "Sirt1, a key regulator of inflammatory processes, reduces atherosclerosis in different animal models." (PMID 23382833, 2013). "Sirt1 regulates transcription factors involved in inflammatory processes and blunts atherosclerosis in mice." (PMID 23382833, 2013). "Particularly, a number of reports indicate that vascular SIRT1 protects vessels from various vascular diseases including atherosclerosis and diabetic vascular complications." (PMID 23056314, 2012). "This is further validated by SIRT1 activation or calorie restriction in ApoE-/- mice leads to protection against atherosclerosis progression by upregulating eNOS." (PMID 20663150, 2010).